CXCL9 (C-X-C motif chemokine ligand 9)
Diseases named in the same sentence as CXCL9 in open-access papers (continued):
Sharing a sentence is not in itself a finding about the gene and the disease.
osteosarcoma (3 papers, 2020 to 2024). A usually aggressive malignant bone-forming mesenchymal neoplasm, predominantly affecting adolescents and young adults. "In the present work, we first identified the relationship between c-Myc inhibition and upregulation of CCL5, CXCL9, and CXCL10 in osteosarcoma." (PMID 35292660, 2022). "Collectively, these results suggested that c-Myc inhibition can promote the regression of osteosarcoma by increasing the expression and secretion of CCL5, CXCL9, and CXCL10 in tumor tissues." (PMID 35292660, 2022). "The results showed that there were significant negative correlations between the c-Myc expression level and those of CCL5, CXCL9, and CXCL10 in human osteosarcoma samples." (PMID 35292660, 2022). "We found that IHC staining exhibits that all the protein expression of CXCL9, CXCL11/CXCR3 axis was significantly elevated in osteosarcoma tissues compared with adjacent normal tissues (bone, marrow, soft tissue and cartilage)." (PMID 32820615, 2020). "Furthermore, our work demonstrated that pharmacological inhibition of c-Myc in osteosarcoma can promote T cell trafficking into tumor beds by increasing the expression and secretion of CCL5, CXCL9, and CXCL10." (PMID 35292660, 2022). "Given that the expression of CCL5, CXCL9, and CXCL10 could be upregulated by a c-Myc inhibitor in the K7M2 model, we then asked whether this regulatory relationship also existed in human osteosarcoma." (PMID 35292660, 2022).
periodontitis (3 papers, 2020 to 2023). An acute or chronic inflammatory process that affects the tissues that surround and support the teeth. "Studies in patients with chronic periodontitis and aggressive periodontitis showed reduced blood levels of CCL5 compared to healthy subjects and reduced plasma levels of CCL11 and CXCL9 in patients with chronic periodontitis." (PMID 38139161, 2023). "Moreover, chemokines such as CXCL8, CXCL10, CXCL12, and CCL5 accumulate in the crevicular fluid of periodontitis patients and their source might be attributed to fibroblasts at least for CXCL2, CXCL3, CXCL8, CXCL9, CXCL10, CXCL12, and CXCL16." (PMID 37762294, 2023).
Q fever (3 papers, 2017 to 2021). A bacterial infection caused by Coxiella burnetii. "In conclusion, CXCL9, as a marker of cell-mediated immunity, is a promising candidate to improve the diagnostic accuracy of chronic Q fever." (PMID 28793883, 2017). "The IFN-γ inducible chemokine CXCL9 is higher in sera from chronic Q fever patients than in people healed from C. burnetii infection, and so it has been proposed as a chronic Q fever biomarker." (PMID 34796128, 2021). "CXCL9 protein, measured in serum or as C. burnetii stimulated production, is a promising biomarker for the diagnosis of chronic Q fever." (PMID 28793883, 2017). "ROC analysis of the CXCL9 serum concentrations of chronic Q fever compared to past Q fever individuals resulted in a test accuracy of 79% (denoted by the AUC, CI 67–92%)." (PMID 28793883, 2017). "Chronic Q fever patients showed higher CXCL9 serum concentrations than past Q fever individuals (median 537 pg/mL, 82–927)." (PMID 28793883, 2017). "CXCL9 production was significantly higher in chronic Q fever patients (median 15.1 ng/mL, IQR 8.5–26.5) than in healthy controls (median 3.6 ng/mL, IQR 1.7–8.2, p < 0.05) and past Q fever patients (median 3.8 ng/mL, IQR 2.8–5.3, p < 0.05)." (PMID 28793883, 2017). "Chronic Q fever patients showed increased production of all four chemokines (CXCL9, CXCL10, CXCL11 and CCL8)." (PMID 28793883, 2017). "In whole blood cultures of chronic Q fever patients, production of all four chemokines was increased upon C. burnetii stimulation, but also healthy controls and past Q fever individuals showed increased production of CXCL9, CXCL10 and CCL8." (PMID 28793883, 2017). "In addition, CXCL9 serum concentrations in chronic Q fever patients were higher than in past Q fever individuals." (PMID 28793883, 2017). "Further analysis of the CXCR3-chemokine serum concentrations revealed that samples taken within one month after diagnosis of chronic Q fever (n = 9) were significantly higher for CXCL9 (p < 0.05) and CXCL10 (p < 0.05) than samples taken more than 1 month after diagnosis (n = 41)." (PMID 28793883, 2017). "Reviewing the results from the current study we can argue that simple measurement of CXCL9 serum concentration may also be of help in distinguishing chronic Q fever from past infection, although its specificity and sensitivity is somewhat lower than the IFN-γ/IL-2 production assay." (PMID 28793883, 2017). "This suggests that particularly CXCL9 could aid in the diagnosis of chronic Q fever." (PMID 28793883, 2017). "Unfortunately, we were unable to test antigen-specific CXCL9, CXCL10, and CXCL11 production in asymptomatic Q fever seropositive controls." (PMID 29804281, 2018). "One limitation is the small group size of QFS patients who recovered from their complaints and missing CXCL9, CXCL10, and CXCL11 data for asymptomatic Q fever seropositive controls." (PMID 29804281, 2018). "Gene expression of the chemokines CXCL9, CXCL10, CXCL11 and CCL8 was strongly up-regulated in C. burnetii stimulated PBMCs of chronic Q fever patients, in contrast to healthy controls." (PMID 28793883, 2017). "A Receiver-operator-curve (ROC) analysis was performed for CXCL9 and CXCL11 to distinguish between chronic Q fever patients and past Q fever patients." (PMID 28793883, 2017). "Additionally, due to an interassay coefficient of variability well above 15%, we had to exclude data for antigen-specific CXCL9, CXCL10, and CXCL11 production in asymptomatic Q fever seropositive controls." (PMID 29804281, 2018). "Furthermore, a recent study has shown a promising role for chemokines CXCL9, CXCL10, and CXCL11 as potential new biomarkers for persistent infection with C. burnetii, i.e. chronic Q fever." (PMID 29804281, 2018). "However, CXCL9 and CXCL11 production was significantly higher for chronic Q fever patients compared to past Q fever individuals." (PMID 28793883, 2017).
Q fever (continued). "C. burnetii-specific IFNy, IL-2, CXCL9, CXCL10, and CXCL11 production were tested in ex vivo stimulated whole blood of QFS patients who recovered from their complaints (n = 8), QFS patients with persisting complaints (n = 27), and asymptomatic Q fever seropositive controls (n = 10)." (PMID 29804281, 2018). "A recent study showed that antigen-specific production of CXCL9 and CXCL11, but not CXCL10, could further help differentiate chronic Q fever patients from Q fever seropositive controls." (PMID 29804281, 2018).
rosacea (3 papers, 2021 to 2023). A chronic erythematous skin disorder that affects the face. "In patients with rosacea, an increase in circulating serum chemokines CXCL9 and CXCL10 was found, which might provide evidence that rosacea is systematically involved." (PMID 36091020, 2022).
skin tumor (3 papers, 2018 to 2025). "We will further investigate the mechanisms regulating DC subset migration into the TME during skin tumor progression and engineer a subset of DCs through Cxcl9/Cxcl10 to further improve the antitumor therapy." (PMID 40282557, 2025). "Further, we found a higher expression of Cxcl9, Cxcl10, and Dpp4 in DCs in skin tumors." (PMID 40282557, 2025). "Consequently, the skin tumor type and a better understanding of the regulation of expression of human CXCR3 isoforms on skin tumor cells and their differential responses to CXCL9/10/11 will dictate if this chemokine receptor/chemokine system can be manipulated to treat skin cancers." (PMID 30320116, 2018).
small cell lung carcinoma (3 papers, 2021 to 2025). Small cell lung cancer (SCLC) is a highly aggressive malignant neoplasm, accounting for 10-15% of lung cancer cases, characterized byrapid growth, and early metastasis. "CXCL9 derived Th1 responses and limited Th2 infiltration, and it was associated with favorable prognosis in small cell lung cancer, however, other studies have reported that CXCL9 binds to CXCR3 in tumors to promote EMT and cancer cell migration." (PMID 38075694, 2023). "In addition, as widely cognitive tumor-suppressor factor, CXCL9 in small cell lung cancer might be a risk factor." (PMID 38075694, 2023). "YKL-5-124, a potent CDK7 inhibitor, activates IFN-γ signaling and induces TNF-a and CXCL9/10 in small-cell lung cancer." (PMID 40175357, 2025). "Moreover, small cell lung cancer research revealed that the CDK7 inhibitor YKL-5-124 activated CXCL9 and that CXCL10 signalling may be a promising outcome of combining YKL-5-124 and anti-PD-1, confirming the pivotal function of CXCL9 in immunotherapy." (PMID 34527583, 2021).
systemic sclerosis (3 papers, 2011 to 2025). A chronic disorder, possibly autoimmune, marked by excessive production of collagen which results in hardening and thickening of body tissues. "This analysis revealed that there was no significant and meaningful (fold change [FC] > 2) upregulation in the expression of SPP1, CCL4, CCL5, and CXCL9 in systemic sclerosis myeloid cells." (PMID 39989459, 2025). "When compared with NL and NXG fibroblasts, systemic sclerosis lesional fibroblasts showed a more modest upregulation of CCL5 and CXCL9." (PMID 39989459, 2025). "Unlike NL-specific fibroblasts, these systemic sclerosis-enriched fibroblast clusters did not overexpress IL32, CCL5, or CXCL9." (PMID 39989459, 2025).
toxoplasmosis (3 papers, 2014 to 2021). A parasitic disease contracted by the ingestion or fetal transmission of toxoplasma gondii. "We then asked if neutrophils could be one of the sources of CXCL8, CCL4, CXCL9, and CXCL10 during toxoplasmosis." (PMID 34607465, 2021). "Moreover, we have also observed that the combined analysis of CXCL9 and CXCL10 improves the accuracy of these biomarkers to diagnose toxoplasmosis." (PMID 33028847, 2020).
uveitis (3 papers, 2012 to 2023). An inflammatory process affecting a part of or the entire uvea. "Notably, our previous induced uveitis rodent studies demonstrated SOCS1-KIR mediated decreases in the chemokines CCL2, CCL20 and CXCL9, in addition to the chemokine receptors CCR2, CCR4, CCR6 and CXCR35,25." (PMID 35505065, 2022). "In conclusion, our study showed that uveitis associated with TB featured increased aqueous levels of IL-6, CXCL2, CXCL8, CXCL9, and CXCL10, which is not typical of an active ocular TB infection." (PMID 22509092, 2012).
acute kidney injury (2 papers, 2017 to 2025). Sudden and sustained deterioration of the kidney function characterized by decreased glomerular filtration rate, increased serum creatinine or oliguria. "However, the lack of specificity with CXCL9/10 with other renal pathologies, such as infection and acute kidney injury, highlight the need for multiple markers, such as exosomal mRNA, along with clinical contexts, to potentially guide clinical decisions." (PMID 40807111, 2025).
Angina (2 papers, 2018 to 2025). "However, the levels of CXCL9, CXCL10, and CXCR3 remained low in patients with unstable angina, comparable to the control group and significantly lower than in patients with stable angina." (PMID 30210493, 2018).
bone cancer (2 papers, 2015 to 2022). A primary or metastatic malignant neoplasm affecting the bone or articular cartilage. "In both the intracardiac and the intratibial injection model, the frequency of BM NK cells, GrB+ NK cells, and Th1 cells was increased by bone tumor growth in control mice but not in those treated with anti-CXCL9 antibody." (PMID 35503658, 2022).
brain tumor (2 papers, 2022 to 2024). "CXCL9 has weak negative causality with daytime nap meanwhile its reduction can be explained by brain tumor." (PMID 39043735, 2024).
cardiac hypertrophy (2 papers, 2024 to 2025). "UUO resulted in cardiac hypertrophy, accompanied by an elongation of the QRS wave on the ECG, decreased expression of Cxcl1, Cxcl9, and Il1b, reduced the number of CD11b+ cells, and increased in titin isoform parameters, such as T1/MHC and TT/MHC ratios, without changes in fibrosis markers." (PMID 40869420, 2025).
celiac disease (2 papers, 2019 to 2025). An autoimmune genetic disorder with an unknown pattern of inheritance that primarily affects the digestive tract. "Especially, the gluten-specific CD4+ T cells are known to express CXCR3, responding to the CXCL9 and CXCL10 that are expressed in the coeliac regions, for which CXCL9 and CXCR are suggested as the therapeutic targets for the coeliac disease." (PMID 39897058, 2025). "For Coeliac disease (CE), CCL25 (cytokine ligand 25) and CXCL9 (chemokine ligand 9) were on the top of the features list." (PMID 39897058, 2025). "CXCL9 and CXCL10 are key regulators of T cell trafficking, and elevated CXCL10 promotes T cell recruitment in celiac disease." (PMID 31481960, 2019).
Cerebral ischemia (2 papers, 2013 to 2025). Restriction of arterial blood supply to the brain associated with insufficient oxygenation to support the metabolic requirements of the tissue. "CXCL9, a chemoattractant for T lymphocytes and NK cells triggered by interferon-gamma, is still not clearly understood in the context of cerebral ischemia." (PMID 38861234, 2025). "Only chemokine ligand-9 (CXCL9), chemokine ligand-11 (CXCL11), and chemokine receptor-1 (XCR1) have not been, to our knowledge, previously examined with their relations to cerebral ischemia." (PMID 24244400, 2013).
chronic lymphocytic thyroiditis (2 papers, 2022). "Moreover, CSF1 induces pro-tumoral M2 macrophage polarization through binding to CSF1R, whereas CXCL9 and CXCL10 are involved in T-cell recruitment manifested as chronic lymphocytic thyroiditis, which has been associated with a better prognosis of PTC." (PMID 35515000, 2022). "Recent studies indicate that chemokines CXCL9, CXCL10 and CXCL11, induced by INF-γ, may play an important role in the early development of Hashimoto’s thyroiditis." (PMID 36139446, 2022).
chronic pancreatitis (2 papers, 2016 to 2022). A chronic inflammatory process causing damage and fibrosis of the pancreatic parenchyma. "Compared with DMBA-treated WT mice, DMBA-treated TG mice showed lower mRNA levels of CD68, a marker of macrophages; Cxcl9, a four-chemokine signature in primary and metastatic PC; and Ccl3, which plays an important role during chronic pancreatitis." (PMID 35504863, 2022). "CXCL9 is a small cytokine that has been shown to play an anti-fibrotic role in experimental chronic pancreatitis in rats and is a promising therapeutic target in pancreatic fibrosis." (PMID 26699651, 2016).
clear-cell renal cell carcinoma (2 papers, 2019 to 2025). "Notably, this C1Q signature was linked to a poor prognosis in clear-cell renal cell carcinoma 22, but CXCL9 attracts CD8+ cytotoxic T cells and is associated with better outcomes." (PMID 40027748, 2025). "It had been reported that the calculated score based on the expression of CXCL11, CXCL9, and CXCL10 could stratify nonmetastatic clear-cell renal cell carcinoma (ccRCC) patients into different risk subgroups." (PMID 31781593, 2019).
coagulopathies (2 papers, 2017 to 2023). "Patients with high CXCL9 levels suffered from more severe disease including a higher prevalence of circulatory shock, myocardial dysfunction, coagulopathy, cytopenia, and higher inflammatory markers compared to patients with low serum levels." (PMID 37046304, 2023).
Cognitive impairment (2 papers, 2023 to 2025). Abnormal cognition is characterized by deficits in thinking, reasoning, or remembering. "Our findings are in line with previous research linking CXCL9 to frailty, sarcopenia, cognitive impairment, and mortality in both community-dwelling individuals and patients with established diseases." (PMID 41419927, 2025). "Chemokines CCL1, CCL2, CCL15, CCL27, CXCL9, CXCL10, and CX3CL1 might be most promising to serve as key molecular markers of cognitive impairment, although more cohort studies with larger populations are needed." (PMID 37291639, 2023).
contact dermatitis (2 papers, 2016 to 2024). An inflammatory skin condition caused by direct contact between the skin and either an irritating substance or an allergen. "Therefore, we investigated the expression pattern of CXCL9 in the skin of mice under inflammatory conditions using a previously established oxazolone (OXA)-induced contact dermatitis model." (PMID 26892362, 2016). "Moreover, CXCL9 is significantly induced in PGRN KO mice in a contact dermatitis model." (PMID 26892362, 2016).
coronary artery calcification (2 papers, 2015 to 2018). Calcification of the coronary artery, used as a measure of coronary atherosclerosis, a risk factor for myocardial infarction. "CXCL9 and other CXCR3 chemokines have been implicated in the regulation of migration of monocytes and lymphocytes and their retention in atherosclerotic lesions, and serum levels of CXCL9 correlate with severity of coronary narrowing as well as coronary artery calcification." (PMID 30563576, 2018).
cystitis (2 papers, 2008 to 2018). Inflammation of the urinary bladder. "CXCL9 protein expression in whole urinary bladder of female mice with 4 h CYP-induced cystitis was significantly greater than that observed following intermediate (48 h) and chronic CYP treatment." (PMID 29681802, 2018). "CXC mRNA transcript expression changes in female mice with cystitis were primarily increases in expression in the urothelium and detrusor for CXCL9 and CXCL10." (PMID 29681802, 2018). "Perhaps in association with the differences between the various forms of IC and murine CYP-induced cystitis, CXCL10 (followed by CXCL9) was higher in mice with CYP-induced cystitis, but CXCL9 (followed by CXCL10) was found to be higher in IC patients." (PMID 18957084, 2008). "CYP-induced cystitis in mice led to substantial increases in serum levels of CXCL10 >> CXCL9 when compared with the levels in unaffected controls." (PMID 18957084, 2008). "The CXC chemokine family is pro-inflammatory with family members CXCL9, CXCL10, CXCL11, and their common receptor, CXCR3, contributing to urinary bladder inflammation." (PMID 29681802, 2018). "In contrast, CXC mRNA transcript expression changes in male mice with cystitis were primarily decreases in expression (CXCL9-11) in the urothelium but both increases (CXCL10) and decreases (CXCL9, CXCL11) in expression were observed in the detrusor." (PMID 29681802, 2018). "In summary, mice with CYP-induced cystitis expressed higher serum CXCL10 > CXCL9 than unaffected controls, while IC patients displayed higher CXCL9 > CXCL10 serum levels than unaffected individuals." (PMID 18957084, 2008). "CXCL9 transcript expression in urothelium of male mice with intermediate (48 h) and chronic CYP treatment was significantly (p ≤ 0.01) decreased compared to acute (4 h) CYP-induced cystitis." (PMID 29681802, 2018). "CYP-induced cystitis in mice led to substantial increases in the expression of CXCL10, CXCL11, and CXCR3 mRNA by urinary bladder leukocytes as well as modest increases in the expression of CXCL9 and CXCR3 transcripts by iliac lymph node lymphocytes than compared to normal, untreated mice." (PMID 18957084, 2008). "Despite the reduction of serum CXCL9 and CXCL10 levels following anti-CXCL10 Ab treatment(s) of mice given CYP, it remained uncertain whether CXCL10 blockade would improve the pathology of cystitis." (PMID 18957084, 2008).
dementia (2 papers, 2022 to 2023). Loss of intellectual abilities interfering with an individual's social and occupational functions. "Increased expression of CXCL9 to CXCL11 is typically induced by antiviral or IFN-associated signaling, which regulates glial functions and is linked to cognitive changes, dementia, and neuropsychiatric disorders." (PMID 37075107, 2023).
diabetic retinopathy (2 papers, 2019 to 2020). "It was recently observed that CXCL9 could activate Jak2/ STAT3 signalling in podocytes and correlates with retina inflammation in patients with diabetic retinopathy." (PMID 31913856, 2020).